RN7SL841P (RNA, 7SL, cytoplasmic 841, pseudogene)
Gene: Miscellaneous RNA gene on chromosome 16 (55,291,379 to 55,291,675, reverse strand). Ensembl gene ENSG00000239555.
Homologues: Orthologues: chimpanzee Metazoa_SRP (99% identical), macaque Metazoa_SRP (90% identical). Paralogues in human: RN7SL1 (79% identical), RN7SL2 (79% identical), RN7SL3 (78% identical), RN7SL709P (78% identical), RN7SL828P (77% identical), RN7SL126P (77% identical), RN7SL83P (76% identical), RN7SL187P (76% identical), RN7SL479P (76% identical), RN7SL566P (76% identical), RN7SL717P (76% identical), RN7SL91P (76% identical), and 702 more.